TET1 (tet methylcytosine dioxygenase 1)
Diseases named in the same sentence as TET1 in open-access papers (continued):
Sharing a sentence is not in itself a finding about the gene and the disease.
gastric cancer (continued). "TET1 binds to the guanine nucleotide‐binding protein subunit beta‐4 (GNB4) promoter region, which promotes gastric cancer proliferation and metastasis by activating the transcription of GNB4 and activation of the Hippo‐Yes‐associated protein 1 pathway." (PMID 40599235, 2025). "In gastric cancer, NUTM2A-AS1 sponges miR-376a, which normally suppresses TET1 and HIF-1A; the resulting increase in these proteins subsequently elevates PD-L1 expression, thereby promoting cell viability, invasion, and chemoresistance." (PMID 40903777, 2025). "On the other hand, TET1 and TET2 are expelled from the nucleoplasm via their nuclear export signals in gastric cancer and small intestinal neuroendocrine tumour cells, respectively." (PMID 38583183, 2024). "Our research work firstly clarified that TET1 up-regulates its target gene PTEN through increasing 5-hmC content of its promoter and eventually represses gastric cancer development." (PMID 27121319, 2016). "In gastric cancer, however, IDH mutants are rather rare, implying that restoration of TET1 expression might be more important than its enzyme activity." (PMID 35805009, 2022). "Among them, an epigenetic regulator TET1 and HIF‐1A were evidently regulated, which could bridge epigenetic mechanism with NUTM2A‐AS1/miR‐376a‐regulated gastric cancer." (PMID 33089970, 2020). "The IHC analysis showed that TET1 expression was reduced in 28 out of 35 gastric cancer samples compared to non-tumor tissues." (PMID 27121319, 2016). "We found that TET1 mRNA was significantly reduced in gastric cancer tissues compared with the surrounding non-tumor tissues (p=0.036)." (PMID 27121319, 2016). "In order to explore TET1 expression level in gastric cancer, we analyzed TET1 mRNA expression in tumor tissues and adjacent non-tumor tissues from gastric cancer patients by real-time PCR." (PMID 27121319, 2016). "As the in vitro culture medium used for migration and invasion assay was serum-free, we concluded that TET1 really suppressed gastric cancer cell migration and invasion rather than through inhibiting cell proliferation." (PMID 27121319, 2016). "Interestingly, knocking-down FOXO4 in TET1-overexpressing cells or overexpressing FOXO4 in TET1-knocking-down cells fully rescued the features of CSC and EMT in gastric cancer cells, suggesting that FOXO4 might be the major player downstream of TET1 to regulate metastasis-promoting Wnt signaling." (PMID 35805009, 2022). "We observed that TET1 can dramatically influence EMT, self-renewal of CSCs and metastasis of gastric cancer cells without dramatically affecting cell proliferation and viability." (PMID 35805009, 2022).
glioma (28 papers, 2013 to 2025). A benign or malignant brain and spinal cord tumor that arises from glial cells (astrocytes, oligodendrocytes, ependymal cells). "A previous study revealed a strong correlation between IDH1 mutations and the nuclear localization of TET1 in glioma cells." (PMID 40520993, 2025). "This study confirmed the tumor suppressive function of TET1 and illustrated the underlying molecular mechanisms regulated by TET1 in glioma." (PMID 34926132, 2021). "In conclusion, our work demonstrates that deficiency of TET1 can promote the tumorgenesis of glioma by upregulating the expression of β-catenin." (PMID 34926132, 2021). "It is found that the deficiency of TET1 in glioma tissues and downregulation of TET1 in U251 and SW1783 cells promoted cell proliferation, migration, and invasion and affected the distribution of cell cycles." (PMID 34926132, 2021). "The lowest quartile of TET1 expression is significantly associated with glioma hazard in a multivariate model of TET1 + age + IDH1 status + Histological type." (PMID 32483272, 2020). "Genes were selected from an earlier study in which gene expression was compared between a human glioma cell line that was made TET1-deficient and a control cell line." (PMID 32483272, 2020). "We recently reported that glioma cell lines deficient with Tet methylcytosine dioxygenase 1 (TET1) exhibited greater genomic instability and were more resistant to ionizing radiation therapy." (PMID 32483272, 2020). "Since TET1 is responsible for the oxidation of 5mC to 5hmC and gliomas with loss of 5hmC expression have been reported to show nuclear exclusion of TET1 expression, we investigated this correlation in SDH and FH mutant tumors." (PMID 26472283, 2015). "Moreover, they find the autophagy level in glioma is regulated by TET1 and deficiency of TET1 in U251 cells inhibits the autophagy and then promotes the proliferation and invasion of U251 cells." (PMID 34926132, 2021). "To test the hypothesis, we modeled mediation relationships between TET1, glioma survival, and eight cancer hallmarks using a linked neural network experiment and data from the Genomic Data Commons." (PMID 32483272, 2020). "In a previous study, we found that cycle checkpoints attenuated in TET1-deficient gliomas." (PMID 32483272, 2020). "Higher numbers of mutations were found in gliomas with low levels of TET1 expression." (PMID 32483272, 2020). "Cytoplasmic localization of TET1 corresponds to loss of 5hmC in gliomas." (PMID 32774324, 2020). "Since we detected loss of 5-hmC in a subset of chondrosarcomas, which was not correlated with IDH mutation status, we evaluated whether, similar to gliomas, loss of 5-hmC was associated with nuclear exclusion of TET1." (PMID 28484589, 2017). "To validate the findings in cell lines carrying intrinsic IDH mutants, we investigated the role of TET1/2 in the DNA damage response and tumorigenicity using patient-derived glioma stem cells (GSCs), BT054, and BT142." (PMID 39920158, 2025). "The study showed that reduced TET1 levels stimulated glioma cell proliferation, migration, and invasion." (PMID 40520993, 2025). "Another study confirmed TET1's role as a tumor suppressor and further elucidated the molecular mechanisms regulated by TET1 in gliomas." (PMID 40520993, 2025). "Their downregulation was significantly higher in Grade IV GBM in comparison with Grade II gliomas (TET1 and TET3 p < 0.001, TET2 p < 0.01) and Grade III gliomas (TET1 p < 0.001, TET2 and TET3 p < 0.01)." (PMID 35494033, 2022). "We showed that the plasma relative mRNA level for TET1 was decreased in every stage of glioma, while the TET3 level remained unchanged." (PMID 35494033, 2022). "In this paper, we conducted the experiments to prove the critical roles TET1 played in glioma and explored the downstream targets of TET1 in order to provide a novel theoretical basis for clinical glioma therapy." (PMID 34926132, 2021).
glioma (continued). "The further experiments in vivo confirmed that TET1 inhibits glioma cell growth by targeting Wnt/β-catenin pathway." (PMID 34926132, 2021). "It is found that downregulation of β-catenin inhibits migration and invasion of glioma cells which are promoted by downregulation of TET1." (PMID 34926132, 2021). "To investigate the expression of TET1 in malignant glioma patients, we detected the relative RNA level of TET1 in WHO grade IV glioma specimens and adjacent normal tissues by RT-qPCR." (PMID 34926132, 2021). "Similar subcellular localization of TET1 has been observed in ovarian endometriotic lesions, gastric and ovarian cancers, hippocampal neurons, and gliomas." (PMID 34844636, 2021). "In accordance with previous studies, our study demonstrates that TET1 is downregulated in malignant glioma (WHO grade IV glioma) specimens, and knock down of TET1 promotes proliferation, migration, and invasion of malignant glioma cells." (PMID 34926132, 2021). "To investigate the molecular mechanisms targeted by TET1 in tumor growth of glioma, we adopted Western blot to detect the expression of cancer-related proteins." (PMID 34926132, 2021). "The TET1 hazard ratio is significant at the 0.001 level for Q1 in all patient categories (lower-grade gliomas, patients under/over 45, male/female patients) except in GBM patients, where a trend was observed." (PMID 32483272, 2020). "The expression of TET1 is greater in tumors that harbor isocitrate dehydrogenase (IDH) mutations in both GBM and low-grade gliomas." (PMID 32483272, 2020). "We confirmed studies by others of the relationship between poorer survival and low levels of TET1 expression in glioma patients." (PMID 32483272, 2020). "Loss of nuclear localization of TET2 has also been reported to occur in colorectal cancer and of TET1 in gliomas." (PMID 30045709, 2018). "Despite this, we confirmed a correlation between loss of 5-hmC and diminished nuclear staining for TET1, which was also found in IDH wildtype gliomas and SDH deficient paragangliomas." (PMID 28484589, 2017). "Real-time RT-PCR analysis of 54 glioma samples showed that TET1 and TET2 mRNA was expressed at varying levels in primary glioblastomas, secondary glioblastomas, and anaplastic astrocytomas." (PMID 24202321, 2013). "Our data combined with these studies suggests that ascorbate may support TET1/2 function in gliomas and lead to increased 5-hmC, but intervention phase 0 trials are first required to assess whether glioma ascorbate content can be manipulated." (PMID 36050369, 2022). "It was found that downregulation of TET1 could promote the proliferation migration and invasion of glioma cells and the concomitant upregulation of β-catenin, and its downstream targets like cyclinD1 and c-myc were observed." (PMID 34926132, 2021). "Bearing in mind that DNA-hypermethylation is often a result of an imbalance of DNA methylation and demethylation which can be based on reduced TET1 protein activity as shown in gliomas, we investigated the protein levels of TET1 and TET2 via immunohistochemistry." (PMID 33917711, 2021). "In our work, we identify the importance of TET1 in the tumorgenesis of glioma." (PMID 34926132, 2021). "In addition, TET1 is found downregulated in glioma specimens, and downregulation of TET1 facilitates proliferation and invasion in glioma cells by inhibiting the cellular autophagy." (PMID 34926132, 2021). "The link between TET1 activity and PD-L1 expression has already been proposed in gliomas." (PMID 34298712, 2021). "In addition, overexpression of β-catenin leads to markedly reduction of glioma cell growth which is enhanced by overexpression of TET1." (PMID 34926132, 2021). "We investigated some patient and tumor characteristics that might modify the effect that TET1 has on glioma patients." (PMID 32483272, 2020).
glioma (continued). "In contrast, the TET1-deficient A172 glioma cell line did not display significant migration at four hours after initializing migration, and at 12 hours migration was observed but significantly differently compared to the control cell line." (PMID 32483272, 2020). "There has also been evidence indicating the involvement of TET1 in glioma growth in humans." (PMID 32483272, 2020). "This study was conducted to test the hypothesis that genes involved in the DDR mediate the poor prognosis of glioma patients with low levels of TET1." (PMID 32483272, 2020). "The hypothesis tested here is that genes involved in the DDR mediate the poor prognosis of glioma patients with low levels of TET1." (PMID 32483272, 2020). "Considering the successes in immune modulation for treating cancers, TET1 is a potential marker for predicting whether the gliomas would be responsive to biological agents that target Il-9 and VTCN1." (PMID 32483272, 2020). "Prasad and colleagues demonstrated that hypoxic environment could induce the demethylation in glioma cells by overexpression of TET1 and TET3, then promoted the stemness of tumor cells by upregulating OCT4 and NANOG expression." (PMID 32014008, 2020). "Additionally, results of Western blot confirmed the downregulation of TET1 in glioma specimens." (PMID 34926132, 2021). "Furthermore, nuclear exclusion of TET1 was shown to be related to loss of 5-hmC in gliomas without IDH mutations." (PMID 28484589, 2017). "IDH protein mutants that are commonly discovered in gliomas and AML are able to convert α-KG to 2HG and inhibit α-KG-dependent enzyme activity, such as TET1." (PMID 35805009, 2022). "Quantitative real-time PCR was performed to examine the mRNA expression of TET family genes (TET1, TET2, and TET3) in 34 samples, including 6 Grade II gliomas, 7 Grade III gliomas and 21 Grade IV GBM." (PMID 35494033, 2022). "To explore the roles TET1 played in tumor growth of glioma, we downregulated TET1 by transfecting glioma cells LN-229 and SW1783 with TET1 shRNA." (PMID 34926132, 2021). "TET1 expression is upregulated in glioblastomas, TET2 is downregulated in gliomas, and TET3 is epigenetically repressed in gliomas." (PMID 33461542, 2021). "The relationship between TET1 and patient survival was observed in both GBM and low-grade gliomas, and both male and female patients saw similar survival curves." (PMID 32483272, 2020). "TET1 is elevated in GBM, while TET2 expression is downregulated in glioma, and TET3 is epigenetically repressed in glioma." (PMID 32244981, 2020). "In fact, high expression of TET1 was found not only in AML, but also in various tumors including uterine cancer, glioma, etc., and especially, in testicular germ cell malignancies." (PMID 29235481, 2017). "Müller and colleagues investigated levels of 5-hmC and the expression of TET1 and TET2 in glioma tissues and cell lines." (PMID 24202321, 2013). "Another possibility is that either TET1 or TET3 drives conversion of 5-mC to 5-hmC in the brain and that their activity is disrupted in glioma." (PMID 24202321, 2013). "In cases where 5hmC was absent, 70 % of gliomas showed either exclusive or predominant cytoplasmic expression of TET1 or lacked detectable TET1 protein altogether." (PMID 40520993, 2025). "We found that TET1, TET2, TET3 mRNA, and 5-hmC levels were decreased during glioma grades." (PMID 35494033, 2022). "TET1 and TET3 bind to Oct4 and Nanog regulatory regions and increase the activity of each transcription factor, thereby promoting the reprogramming of glioma cells to glioma stem cells." (PMID 33585477, 2021). "In addition, the treatment of glioma cells with GANT61 resulted in decrease of mRNA and protein levels of tet1, involved in DNA demethylation and cell reprogramming." (PMID 30730955, 2019). "In addition, all six glioblastoma cell lines examined showed nuclear exclusion of TET1, whereas TET2 was detected in the nuclei of all glioma samples and cell lines." (PMID 24202321, 2013).
glioma (continued). "Of the 5-hmdC negative tumors, 70% showed nuclear exclusion of TET1, or no detectable TET1 protein, thereby demonstrating an additional mechanism that may lead to decreased 5-hmdC in glioma." (PMID 35386689, 2022). "Recently it was shown that TET1 upregulation might be responsible for the elevated levels of 5hmC in proneural glioma subtypes, in case when none of the tumor samples represented IDH mutant status." (PMID 31311166, 2019).
hepatocellular carcinoma (27 papers, 2013 to 2025). A malignant tumor that arises from hepatocytes. "Decreased levels of 5hmC and TET1 expression have also been observed in hepatocellular carcinoma and melanoma, in which 5hmC level is associated with tumor progression and overall survival of patients." (PMID 35805009, 2022). "Survival analyses with the univariate Cox regression model revealed their crucial roles in the patient outcomes, of these, DNMT3A, UHRF1, DNMT1, DNMT3B and TET1 the risk factors for hepatocellular carcinoma." (PMID 35771147, 2022). "Researchers have discovered that TET1 expression is reduced in hepatocellular carcinoma (HCC) tissues, indicating its potential role as a tumor suppressor." (PMID 40520993, 2025). "ALDOB downregulation, on the other hand, is associated with multiple malignant characteristics of HCC, partly through TET1 expression, and could thus be considered a prognostic biomarker for hepatocellular carcinoma, particularly at the early stage of disease." (PMID 36276846, 2022). "MiR-494 has been reported to be able to inhibit TET1 gene expression through targeting its 3′UTR region in human hepatocellular carcinoma (HCC)." (PMID 27557497, 2016). "When TET1 expression was reduced in hepatoma cell lines, cell growth was suppressed." (PMID 40520993, 2025). "However, the precise mechanism by which TET1 regulates sorafenib resistance in hepatocellular carcinoma (HCC) remains to be elucidated." (PMID 38967794, 2024). "In hepatocellular carcinoma, the upregulation of TET1 could drive cell growth through aberrant enhancer hydroxymethylation of HMGA2." (PMID 36195596, 2022). "MiR-29b family is proved to inhibit hepatocellular carcinoma cell migration by targeting TET1." (PMID 32493490, 2020). "In addition, we have reported that circTRIM33–12 inhibits hepatocellular carcinoma proliferation, invasion, and immune system evasion by inhibiting oncogenic miR-191 and promoting tet methylcytosine dioxygenase 1 (TET1) expression." (PMID 31815619, 2019). "Available studies have confirmed that TET1 expression is suppressed in hepatocellular carcinoma (HCC), cells cultured in vitro, and some rapidly proliferating hepatocytes after hepatectomy, yet there is no significant change in TET1 transcript levels." (PMID 34656178, 2021). "Tumor suppressor genes (TSGs), including Ten-eleven translocation 1 (TET1), are hypermethylated in hepatocellular carcinoma (HCC)." (PMID 30551127, 2018). "Upregulation of the demethylating enzyme TET1 inhibits HCV-induced tumorigenesis, proliferation, migration, and invasion; reduces inflammatory mediators in hepatocellular carcinoma; and promotes autophagy and apoptosis." (PMID 41465470, 2025). "Chronic ethanol consumption has also been shown to cause reduced expression of TET1, and the resulting decrease in DNA hydroxymethylation can contribute to hepatocyte apoptosis, ALD progression, and the development of hepatocellular carcinoma (HCC)." (PMID 38389820, 2023). "Since TET1-CD can induce genome-wide DNA demethylation, it is possible that oncogenes such as C-myc, Bmi1, EMS1, Kpna2 and c-fos in hepatocellular carcinoma epigenetics are also activated so as to weaken TET1-CD anticancer activity." (PMID 30551127, 2018). "We found that TET2 expression was up‐regulated in serum‐starved hepatoma cells, while the expression of TET1 and TET3 did not change." (PMID 37752791, 2023). "Our data clearly show that the expression and activity of TET2 and TET3 proteins but not TET1 are impaired in hepatocellular carcinoma leading to the reduction of 5hmC in HCCs." (PMID 26366235, 2015). "The role of TET1 in hepatocellular carcinoma has not been thoroughly investigated." (PMID 34656178, 2021).
hepatocellular carcinoma (continued). "Among the three TET genes, TET1 and TET2 expression levels have frequently been shown to be low in hepatocellular carcinoma (HCC) tissues and received most attention." (PMID 31033072, 2019). "A study of hepatocellular carcinoma observed decreased expression of TET1, but not TET2 and TET3." (PMID 29849955, 2018). "When we looked at the physiological functions of the TET proteins and their mechanisms of regulation of DNA methylation and transcription, out of the three TET genes TET1 and TET2, expression levels were shown to be low in hepatocellular carcinoma (HCC) tissues." (PMID 36030244, 2022). "A study of hepatocellular carcinoma (HCC) has shown that only TET1 expression was decreased in tumors relative to non-tumor tissues, indicating that TET1 has an important function in converting 5-mC to 5-hmC in hepatocellular cells." (PMID 26093090, 2015).